BMP6 (bone morphogenetic protein 6)
Diseases named in the same sentence as BMP6 in open-access papers (continued):
Sharing a sentence is not in itself a finding about the gene and the disease.
breast cancer (continued). "In summary, a shift in the expression pattern of BMPs in breast cancer, including increased BMP8A, BMPR1B and decreased BMP6, BMP7, ACVR1C, TGFBR2, TGFBR3 and BMPR2 presented a subtype specific role." (PMID 37333824, 2023). "It has been shown that BMP6 and BMP7 can suppress oestrogen-promoted proliferation of the MCF-7 breast cancer cell line." (PMID 37333824, 2023). "The present study showed BMP8B was significantly increased in breast tumours, while BMP6 and ACVRL1 were decreased in breast cancer tissues." (PMID 37333824, 2023). "In our work, TOX3 promoted estrogen biosynthesis by upregulating genes related to the development of breast cancer, including FSHR, CYP19A1, and BMP6." (PMID 33716953, 2020). "It is an important regulator of cell growth, differentiation, and apoptosis in various types of tumor (Reduced BMP6 expression by DNA methylation contributes to EMT and drug resistance in breast cancer cells." (PMID 32147967, 2020). "The only references in such regard is that activation of NF-κB by Wnt5a was shown to be required for BMP-6 mRNA and MMP7 upregulation in LNCaP and breast cancer cells, respectively." (PMID 31510045, 2019). "BMP8B was significantly active in primary breast cancer, while BMP2, BMP4, BMP5, BMP6, BMP8B were significantly active in liver metastasis." (PMID 31557971, 2019). "We show that stable overexpression of Smad6 in breast cancer MCF10A M2 cells inhibits BMP signalling, thereby mitigating BMP6-induced suppression of mesenchymal marker expression." (PMID 27113436, 2016). "Bone morphogenetic protein 6 (BMP6), on the other hand, was under-expressed in breast cancer tissues." (PMID 24550697, 2014). "BMP6 has been detected in some breast cancer cells and primary tumors and BMP7 has been reported to be present in different primary breast cancers." (PMID 22729646, 2012). "Quantitative RT-PCR was used to determine the expression of BMP-6, E-cadherin, and δEF1 at the mRNA level in MCF-7 and MDA-MB-231 breast cancer cells, as well as in 16 breast cancer specimens." (PMID 17997862, 2007). "Human breast cancer cell lines were stimulated with BMP2 and/or BMP6 to examine whether reversing the reduced BMP ligand expression could have an impact on β-CATENIN levels." (PMID 38731813, 2024). "BMP6 and BMP7 inhibited estrogen‐induced breast cancer cell proliferation, which could be accomplished by inhibiting p38 mitogen‐activated protein kinase activation." (PMID 37313693, 2023). "In four main subtypes of breast cancer, elevated expression of BMPR1B and ACVR2B were seen in Luminal A subtype, while BMP4, GDF15 and ACVR1B were higher in Luminal B, TGFBR1 and BMP8A were higher in HER2 positive, BMP2, BMP6 and GDF5 were higher in TNBC." (PMID 37333824, 2023). "BMP6 was positively correlated with EMTs in Luminal and HER2 positive breast cancer." (PMID 37333824, 2023). "For example, E2 induces BMP6 in human osteoblastic cells, ER-positive breast cancer cells, and hepatocytes, but not in mesenchymal cells." (PMID 36768740, 2023). "Furthermore, BMP6 was down-regulated in drug-resistant cells, and knockdown of BMP6 in MCF-7 cells enhanced the chemoresistance to doxorubicin, indicating that BMP6 was a critical regulator of breast cancer drug resistance." (PMID 36532723, 2022). "Moreover, prior studies in pancreatic cancer, lung cancer, breast cancer, and CRC demonstrate that miR‐192 regulates expression of SERPINE1, RB‐1, BMP‐6, and DHFR and functions as a tumor suppressor." (PMID 33037736, 2020). "Similar to the analysis of BMP6 expression, the data suggest that Snail1 may regulate CPED1 expression in all subtypes of breast cancers." (PMID 29729076, 2018). "To extend the data generated from the Hs578T cell model, we queried all the human breast cancer cell models included in the GOBO database and identified 19 cell lines in which high‐level Snail1 correlated with high BMP6 or, inversely, low‐level Snail1 correlated with low‐level BMP6." (PMID 29729076, 2018).
breast cancer (continued). "To investigate a potential involvement of the BMP family in telomerase activity, we examined the effects of BMP2, BMP4, BMP5, BMP6 and BMP7 on telomerase activity by spiking the medium of cultured human breast cancer MCF-7 cells with purified recombinant human cytokines." (PMID 27696331, 2017). "BMP-4, BMP-6, and BMP-9 have been reported to inhibit metastasis in breast cancer." (PMID 27661009, 2016). "When the co-culture was treated with BMP6, MDA-MB-231 cells not only adhered better to the HMECs, but the breast cancer cells also formed tightly packed areas where multiple cells are stacked on top of each other This co-culture phenotype mimics the clusters formed in vivo by BMP6-treated cells." (PMID 27113436, 2016). "BMP6 and BMP9 affect the bone metastasis of prostate cancer and breast cancer respectively." (PMID 26029998, 2015). "Comparison of methylation profiles of the 12 breast cancer candidate genes in the paired lymph node metastasis to the matched normal tissue showed significantly higher methylation levels for APC, BMP6, BRCA1 and P16 genes (P < 0.05 and P < 0.01, P < 0.0001, P < 0.05; respectively)." (PMID 22695536, 2012). "Moreover, BMP-6 expression is higher in the ER+ breast cancer cell line, MCF-7, compared to the ER- breast cancer cell line, MDA-MB-231." (PMID 17997862, 2007). "This implies that the downregulation of BMP2 and BMP6 might affect the survival and progression of breast cancer regardless of molecular subtype." (PMID 38731813, 2024). "In summary, our present study provided evidence that BMP6 is a potential target for overcoming MDR in breast cancer, and GA5 could overcome MDR by increasing BMP6 expression, suggesting that GA5 had the potential in the treatment of multidrug resistant breast cancer." (PMID 36532723, 2022). "BMP-6 expression was also absent in breast cancer tissues and might suppress breast cancer metastasis." (PMID 27661009, 2016). "To achieve a gene panel for developing a breast cancer blood-based test we quantitatively assessed the DNA methylation proportion of 248 CpG sites per sample (total of 31,248 sites in all analyzed samples) on 10 candidate genes (APC, BIN1, BMP6, BRCA1, CST6, ESR-b, GSTP1, P16, P21 and TIMP3)." (PMID 21283676, 2011). "Furthermore, higher levels of BMP2, BMP6 and GDF5 were revealed in triple negative breast cancer (TNBC) whilst BMP4, GDF15, ACVR1B, ACVR2B and BMPR1B were relatively higher in Luminal type BC." (PMID 37333824, 2023). "The contribution of aberrant methylation alterations of BMP6, BRCA1 and P16 genes in lymph node metastasis might provide a further clue to establish useful biomarkers for screening metastasis, which might improve prognosis and therapeutic management of the breast cancer patients." (PMID 22695536, 2012). "On the other hand, Reverse Phase Protein Array (RPPA) data for the breast cancer patient cohort, where it is possible to analyze the change in β-CATENIN protein level, did not include either BMP2/BMP6 or phosphorylated SMADs (SMAD1/SMAD5) or direct target genes of BMP pathway such as ID1–3." (PMID 38731813, 2024).
prostate carcinoma (26 papers, 1998 to 2025). A carcinoma that arises from epithelial cells of the prostate gland. "BMP6 causes tumour angiogenesis and proliferation via stimulating IL-Iα in prostate cancer." (PMID 37333824, 2023). "METAP2-PIK3C2G in tumor T17 resulted in the seven-fold upregulation of in-frame PIK3C2G, while FARS2-BMP6 in tumor T9 may also be relevant since BMP6 is linked to invasion of prostate cancer cells." (PMID 25155515, 2014). "Moreover, studies showed an association between BMP6 and skeletal metastases in prostate cancer." (PMID 36532723, 2022). "Using Mendelian randomisation (MR) analysis, it is found that there was a significant correlation between prostate hyperplasia (ukb‐b‐7469) and prostate cancer (ukb‐b‐7773) in the SNP site of BMP6 gene based on the MR Egger algorithm." (PMID 39789383, 2025). "Using SMR software, thousands of Europeans with genomes as reference and eQTLGen data (EQTLgen‐CIS‐EQTLS) and prostate cancer GWAS data for gene colocalisation analysis, we showed the results of prognostic model‐related genes (BMP6 and CRIP2)." (PMID 39789383, 2025). "Bone metastasis of prostate cancer acquired resistance to androgen deprivation through WNT5A‐mediated BMP‐6 induction." (PMID 39789383, 2025). "Through performing MR analysis, it is found that there was a significant correlation between prostate hyperplasia and prostate cancer in the SNP site of BMP6 gene based on the MR Egger algorithm, such as rs2743987, rs7768988." (PMID 39789383, 2025). "Bone morphogenetic protein (BMP)-6 released by prostate cancer cells stimulates M2-type-TAMs to produce IL-6, while tumor-infiltrating M2-type-TAMs promote NED development by activating downstream IL-6 signaling." (PMID 37142586, 2023). "For example, WNT signaling was found to induce BMP4 and BMP6 expression in prostate cancer cells, which in turn stimulated osteoblast differentiation." (PMID 36054271, 2023). "Deeper intricacies are unveiled as BMP6 assumes a central role, conducting a sophisticated symphony of migration and invasion within the domain of prostate cancer cells." (PMID 38049682, 2023). "Further, it has been reported that adding BMP6 to prostate cancer cells inhibits cancer cell growth by activation P21, P18 and P19 expression in the cells." (PMID 35907860, 2022). "In parallel, IL-6 acts on BMP-6 secreting malignant cells and enhances the expression of the androgen receptor, a major determinant of tumor growth and treatment response in prostate cancer." (PMID 33842333, 2021). "In prostate cancer, BMP-6 produced by neoplastic cells acts on adjacent macrophages and activates NF-κB and SMAD1 signaling to increase IL-1α and IL-6 secretion." (PMID 33842333, 2021). "In prostate cancer, BMP6 signaling appears to promote cancer progression, while BMP7 induces quiescence in metastatic cancer cells." (PMID 32894216, 2020). "They found that BMP-6 mRNA was detected in 11 out of 13 bone metastases from samples of prostate carcinoma patients." (PMID 31137764, 2019). "Several tumor-derived molecules have been demonstrated to enhance osteoblast activity, including primary prostate cancer-derived BMP6." (PMID 29642534, 2018). "WNT-5A expressed by bone marrow stromal cells induces expression of BMP-6 in prostate cancer cells via a PKC-NFκB pathway." (PMID 26514730, 2016). "It is well known that BMPs enhance the invasiveness of cancer cells in vitro and in vivo and BMP6 expression correlates with the metastatic potential of prostate cancer." (PMID 26598555, 2016). "For example, in prostate cancer, BMP-6 promotes osteoblastic activity of prostate cancer cells and confer them with a more invasive phenotype." (PMID 25897433, 2015). "BMP-6 is highly expressed in prostate cancer to bone metastases, and a high level of BMP-6 in prostate cancer cells promotes osteoblastic activity of bone cells." (PMID 20010941, 2010).
prostate carcinoma (continued). "On the other hand, the contribution of BMP-6 to tumor metastasis has been recently studied in prostate cancer, suggesting that BMP-6 plays an important role in regulating tumor cell invasion." (PMID 17997862, 2007). "BMP-6 mRNA was detected in 11 out of 13 bone metastases from prostate carcinoma and in three paired samples of primary prostate carcinoma and matching skeletal metastasis." (PMID 9820184, 1998). "We have reported previously that BMP-6 mRNA and protein are expressed in the majority of primary prostatic carcinomas with established skeletal metastases but rarely in clinically organ-confined tumours." (PMID 9820184, 1998). "In a recent study, overexpression of BMP-6 was shown to be correlated with increased Id-1 expression, suggesting that Id-1 might work downstream of BMP-6 in promoting prostate cancer progression." (PMID 20010941, 2010). "Our findings suggest that BMP-6 may hold potential as an attractive marker and possible mediator of skeletal metastases, particularly in prostate carcinoma." (PMID 9820184, 1998). "In addition, expression levels of some genes associated with the progression of prostate cancer, such as relaxin, vascular endothelial growth factor (VEGF), vimentin and bone morphogenetic protein-6 (BMP-6), were significantly downregulated in LNCaP/IL-6#1 compared with LNCaP/Co." (PMID 19844233, 2009). "Amplifying its significance, BMP6 intricately coordinates the heightened expression of MMP and ID1, propelling prostate cancer cells towards an elevated prowess in migration and invasion." (PMID 38049682, 2023). "It was also observed 1,25(OH)2D3 or vitamin D analog regulated mRNA expression of several BMP forms i.e., BMP6 in primary prostate cancer cells, BMP2 and BMP6 in MCF10AT1 cells, and TGFβ1 and BMP2A in squamous cell carcinoma lines." (PMID 34208589, 2021). "Co-cultures of macrophages with prostate cancer cell lines were shown to activate BMP-6/IL-6 loop, where BMP-6 secreted by prostate cancer cells induced expression of IL-6 in macrophages." (PMID 33572108, 2021). "For example, BMP6, a member of the BMP5/6/7 subfamily, is upregulated in prostate cancer and contributes to cancer progression." (PMID 32894216, 2020). "Disseminated prostate cancer cells also indirectly induce MSC to osteoblast differentiation and enhance osteoblast activity by secreting IL6, which stimulates BMP2 and BMP6 from HPCs." (PMID 29642534, 2018). "BMP-6, in turn, activates SMAD and β-catenin signaling to promote proliferation in prostate cancer cells." (PMID 26514730, 2016). "WNT-5A induced BMP-6, thus contributes to the proliferation of prostate cancer cells in the absence of androgens." (PMID 26514730, 2016).
anemia (21 papers, 2013 to 2024). A reduction in the number of red blood cells, the amount of hemoglobin, and/or the volume of packed red blood cells. "Even in patients with anemia and inflammation, hepcidin expression was regulated by iron availability and associated with signals through bone morphogenic protein (BMP)-6 instead of inflammatory stimuli." (PMID 38883134, 2024). "In hypotransferrinemic mice with severe anemia and hepcidin deficiency, the marked hepatic iron overload is also associated with a significant increase in hepatic Bmp6 expression." (PMID 23565256, 2013). "BMP-6 may have a potentially beneficial role in the treatment of anemia caused by excess hepcidin, and the use of BMP-6 agonists is considered in the treatment of iron overload disorders." (PMID 37755286, 2023). "The use of BMP-6 antagonists may have a beneficial effect in the treatment of anemia caused by excess hepcidin." (PMID 37755286, 2023). "We hypothesized that the increased anemia in the Keap1-KD mice was at least in part caused by the documented Nrf2-dependent transcription of bone morphogenetic protein 6 (Bmp6) in liver sinusoidal endothelial cells." (PMID 34526660, 2021). "Similarly, an inhibitory anti-RGMC antibody was shown to reverse anemia caused by high Hepcidin level (up-regulated by BMP6 signaling) in mammals (42, –44)." (PMID 32576689, 2020). "Anti-BMP6, which is highly effective at suppressing hepcidin, increased iron availability and improved haemoglobin in 5TGM1 myeloma-bearing mice, suggesting a specific role for BMP6 in the anaemia associated with myeloma." (PMID 31586071, 2019). "ACVR1 plays a vital role in the production of blood cells and the development of anemia by influencing the BMP6/ACVR1/SMAD pathway, which regulates the expression of hepcidin, a key controller of iron balance in the body." (PMID 38983933, 2024). "Neutralizing antibodies of BMP-6 have been widely used to block hepcidin production in preclinical and clinical models of anemia in chronic diseases, such as chronic kidney disease, which also exhibit a potential role in reducing the need for EPO." (PMID 37208766, 2023). "Erythroferrone and Bone Morphogenetic Protein 6 (BMP-6) are recently identified cytokines involved in the process of increased erythropoiesis in anemia of various pathomechanisms." (PMID 37755286, 2023). "In conclusion, the presented results confirm an increase in erythroferrone concentration in the entire group of IBD patients with anemia, while BMP-6 levels were significantly higher only in patients with CD and anemia compared to the control group." (PMID 37755286, 2023). "For example, LY3113593, a humanised anti-BMP6 monoclonal antibody, whose mechanism of action is to neutralise BMP6, was shown to be effective in the treatment of anaemia in patients with CKD." (PMID 37686128, 2023). "Given this paradoxical role of BMP-6 in anemia and cancer, the efficacy of BMP-6 inhibition for the treatment of cancer-associated anemia requires further investigation." (PMID 37208766, 2023). "Regarding BMP-6, higher levels were found in CD patients with anemia compared to the control group (p = 0.021)." (PMID 37755286, 2023). "Due to the insufficient sensitivity of other markers in the differential diagnosis of anemia in IBD, high expectations were associated with the determination of hepcidin, as well as new laboratory parameters including erythroferrone and BMP-6 levels." (PMID 37755286, 2023). "On the other hand, erythroferrone and BMP-6 are recently identified proteins involved in the process of increased erythropoiesis in anemia of various pathomechanisms." (PMID 37755286, 2023). "In conclusion, we confirm an increase in erythroferrone concentration in the entire group of IBD patients with anemia, while BMP-6 levels were higher only in anemic CD patients." (PMID 37755286, 2023).